CTSH (cathepsin H)
Diseases named in the same sentence as CTSH in open-access papers (continued):
Sharing a sentence is not in itself a finding about the gene and the disease.
respiratory disease (1 paper, 2025). "CTSH was also identified as a differentially expressed gene for bovine respiratory disease in a population of Xinjiang calves." (PMID 40822650, 2025).
CTSH also shares sentences with these, for which no sentence is quoted: osteosarcoma (2 papers); amyloid (1); amyotrophic lateral sclerosis (1); asthma (1); astrocytomas (1); atopic dermatitis (1); Azoospermia (1); cataract (1); celiac disease (1); cyst (1); Dent disease (1); experimental autoimmune encephalomyelitis (1); gall bladder cancer (1); gastric cancer (1); glaucoma (1); Huntington disease (1); hypothyroidism (1); inflammatory bowel disease (1); late-onset Alzheimers disease (1); malaria (1); metabolic disorders (1); myopia (1); non-small cell lung carcinoma (1); oesophageal cancer (1); periodontal disease (1); polycystic kidney disease (1); scleroderma (1); senile cataract (1); skin squamous cell carcinoma (1); T-cell lymphoma (1).
A further 2 diseases each share a sentence with CTSH in 1 paper.